PAX5 (paired box 5)
Diseases named in the same sentence as PAX5 in open-access papers (continued):
Sharing a sentence is not in itself a finding about the gene and the disease.
leukemia (continued). "Here, we have generated a mouse model to investigate the oncogenic role of the Pax5‐Jak2 protein in leukemia formation." (PMID 35156727, 2022). "Combining E2A/PBX1 with Pax5 deletion increased the penetrance and shortened the latency of leukemia." (PMID 34484175, 2021). "Repression of Pax5 shRNA expression by doxycycline treatment removes a block in differentiation and when these established leukemias are transplanted into Rag1-/- recipients, doxycycline treatment causes remission of disease." (PMID 34484175, 2021). "Our results identified a subgroup of cases clustering with known leukemia subtypes, e.g., DUX4-positive, and subgroups characterized by mutations in PAX5 and IKZF1, resulting in more cases being assigned to a defined subgroup." (PMID 34830809, 2021). "For instance, Stat5b-CA x Ebf1+/− and Stat5b x Pax5+/− transgenic mice develop rapid onset leukemia with complete penetrance whereas leukemogenesis is somewhat less efficient when crossing Stat5b-CA with Rag2−/− or μMT−/− mice." (PMID 34736527, 2021). "In contrast to above mouse model, more physiological infectious stimuli induce overt leukemia in a Pax5+/− mouse independently of AID expression." (PMID 33507341, 2021). "Altogether, our data indicate that IL7R mutant-driven leukemias are either PAX5 P80R or Ph-like, in accord with these subtypes being enriched within mutant IL7R patients." (PMID 34907175, 2021). "Kataegis occurred particularly frequently at a per-sample level between chr20:31050000-31080000 which corresponds to the region of NOL4L/C20orf112 (chr20:31,030,862-31,071,385) a known fusion partner of RUNX1 and PAX5 in leukaemia." (PMID 33632293, 2021). "Accordingly, even partial downregulation of PAX5 in the BM resulting from monoallelic deletion promoted p190-driven leukemia with much higher penetrance and earlier disease onset than in mice with normal PAX5 expression (90% vs. 13% incidence)." (PMID 32806528, 2020). "In order to further identify somatically acquired 2nd hits leading to leukemia development, we next performed whole exome sequencing of 4 IL-6+/-/Pax5+/- B-ALLs and corresponding germline on a HiSeq 2500 (Illumina) platform." (PMID 33154497, 2020). "We then characterized the global expression signature of IL-6+/-/Pax5+/- B-ALLs and compared it with the expression signature of both healthy WT pro-B/pre-B cells and IL-6+/+/Pax5+/- leukemias." (PMID 33154497, 2020). "The results showed that the reduction on IL-6 levels significantly delayed the emergency of leukemias in Pax5+/- mice upon exposure to natural infections." (PMID 33154497, 2020). "This idea is supported by the findings that mutant forms of human PAX5 are functionally impaired and that restoration of PAX5 expression in a human leukemia cell allows for a progressive maturation of the B-ALL like cells and loss of malignant phenotype." (PMID 31381561, 2019). "This has been verified in mouse models where heterozygote deletion of Pax5 in combination with expression of constitutively active STAT5 or partial inactivation of the Ebf1 gene largely increase leukemia formation." (PMID 31381561, 2019). "Gene expression analysis of mouse models and primary human leukemia suggested that reduced function of PAX5 increased the ability of an oncogenic form of IKZF1 or ETV6-AML to modulate gene expression." (PMID 31381561, 2019). "It has been reported that the level of PAX5 regulates the formation of bi-phenotypic leukemia and that B-ALL cells carrying mutations in Pax5 can be converted into other lineages with preserved malignant features." (PMID 29966360, 2018).
leukemia (continued). "Here, we report an extremely rare case of BCP-ALL harboring two concomitant leukemia-associated alterations: TCF3-PBX1 and PAX5 rearrangement (PAX5-r)." (PMID 30563523, 2018). "We found Pax5 mRNA levels in Day 16 leukemia cells to be significantly lower compared to WT pre-B cells." (PMID 29740160, 2018). "PAX5 is a known tumor suppressor with a highly conserved DNA‐binding motif that is often involved in leukemia development, however, most frequently through translocations." (PMID 29572294, 2018). "Rather, CD19-expressing B-ALL cells are continuously being deleted under this pressure, until leukaemia either downregulates CD19 (in two of our samples) or reprograms via downregulation of PAX5 and EBF1 to drive a CD19 CAR-resistant relapse." (PMID 27460500, 2016). "Pol2 stalling and convT strongly associate with recurrent breakpoint sites across the genome and at gene loci implicated in leukemia such as CDKN2A and PAX5." (PMID 27431763, 2016). "Transcriptomics analysis of this model was used to understand the transcription response to PAX5 restoration in B-ALL leukaemia cells." (PMID 25631385, 2015). "Although PAX5 fusion genes significantly affect the transcription of PAX5 target genes, their role in sustaining leukemia cell survival is poorly understood." (PMID 25595912, 2015). "Later experiments showed that removal of PAX5 opened way for trans-differentiation into various myeloid cell types and to leukaemia development." (PMID 23828660, 2013). "Many deletions (i.e., Cdkn2a, Ebf1, Pax5, Ikzf1) involved B-cell development genes and tumor suppressor genes, recapitulating deletions occurring in human leukemia." (PMID 23487523, 2012). "Moreover, this suggests a stepwise process of PAX5 inactivation during leukemia development, clearly recapitulated in familial BCP-ALL cases with heterozygous PAX5 germline variants, including PAX5 p.G183S and PAX5 p.R38H." (PMID 40394211, 2025). "Among the transcription factors, PAX5 genetic changes including the mutation p.P80R are frequently seen in B‐ALL/LBL, and these genetic changes are thought to affect B‐cell programming, thereby contributing to leukaemia development." (PMID 41047873, 2025). "Finally, leukemia 241 stood out through high Ly6a (Sca1) and Dntt expression and very little remaining Pax5 transcript levels." (PMID 40394211, 2025). "None of the patients with identified FLT3 mutations presented recurrent rearrangements in B-ALL or alterations in the IKZF1, PAX5, or ERG genes, suggesting that FLT3 mutation may serve as the driving mechanism for leukemia in these cases." (PMID 39711880, 2024). "Indeed, a preleukemic B-cell-dependent role was evidenced by an increase in B-ALL incidence upon Myd88 downregulation in the leukemia-prone Pax5+/− model." (PMID 37620322, 2023). "PAX5 encodes a transcription factor associated with leukemia and, to our knowledge, has not been studied in β cells." (PMID 36656641, 2023). "A higher incidence of leukemia occurred after introducing additional genetic defects through methods such as chemical mutagenesis, Sleeping Beauty transposon expression, or crossbreeding with mice harboring Pax5 or Cdkn2a/b deletions." (PMID 38136366, 2023). "However, consistent with our previous findings, 23% (8 out of 35) of Pax5+/− mice receiving vehicle developed and succumbed to leukemia." (PMID 37620322, 2023). "Furthermore, Pax5 heterozygosis can enhance the expression of inflammatory cytokine interleukin−6 (IL−6), which then promote proliferation of leukemia cells." (PMID 36387144, 2022). "Moreover, chemically-N-ethyl-N-nitrosourea (ENU) and retrovirally mediated Moloney murine leukemia retrovirus (MMLV) mutagenesis in Pax5+/− mice resulted in a significantly increased penetrance of leukemia." (PMID 35886910, 2022). "We next investigated whether the DNA‐binding activity of Pax5‐Jak2 is essential for leukemia formation." (PMID 35156727, 2022).
leukemia (continued). "We next investigated whether the kinase activity of Pax5‐Jak2 is essential for leukemia development." (PMID 35156727, 2022). "In summary, we conclude that the loss of Pax5 expression was not strictly required for leukemia formation, although it clearly accelerated tumor development." (PMID 35156727, 2022). "Recent large scale analyses of the common integration sites of two BCL2 transgenic strains infected with Moloney MuLV (MoMuLV) shows a statistically significant bias toward verified drivers of human B lymphoma and leukemia (Pou2f2, Pax5, Ikzf3, Ebf1) in addition to dozens of other candidate loci." (PMID 34484175, 2021). "Here, we demonstrate that lymphoid-restricted mutant IL7R, expressed at physiological levels in conditional knock-in mice, establishes a pre-leukemic stage in which B-cell precursors display self-renewal ability, initiating leukemia resembling PAX5 P80R or Ph-like human B-ALL." (PMID 34907175, 2021). "Indeed, the production of inflammatory cytokines triggered by infection can promote leukemia growth in Pax5+/− mice." (PMID 34771671, 2021). "It was further shown that the composition of the gut microbiome varied between Pax5+/− mice, which stayed healthy, and Pax5+/− mice, which developed leukemia, but a specific microbe connected with the development of pB-ALL could not be identified." (PMID 35004601, 2021). "If the nature of the second hit confers tumor cell identity to ETV6-RUNX1+ leukemia, we hypothesized that ETV6-RUNX1+ B-ALLs triggered by the loss of either Pax5 or Kdm5c should differ from one another." (PMID 34336858, 2021). "Interestingly, combined heterozygous deletion of Pax5 and Ebf1 partially blocks the differentiation of pro-B cells and increases their lineage plasticity before the leukemia onset." (PMID 34771671, 2021). "This fact appears to be responsible for the association of Pax5 deletion with biphenotypic leukemias rather than an earlier cell of origin of the leukemia stem cell." (PMID 34736527, 2021). "Here, we demonstrate that Pax5 heterozygosis, in the presence of infections, results in the enhanced production of the inflammatory cytokine interleukin-6 (IL-6), which appears to act in an autocrine fashion to promote leukemia growth." (PMID 33154497, 2020). "Hence, while ETV6-RUNX1 expression in primary human leukemia cells associates with altered expression of a substantial fraction of the RUNX1 target genes, reduced function of IKZF1 or PAX5 had limited impact on the expression of their target genes." (PMID 31381561, 2019). "In order to further identify somatically acquired 2nd hits leading to leukemia development in both Pax5-het/Aid-het and Pax5-het/Aid-KO B-ALLs, we performed whole-exome sequencing of five Pax5-het/Aid-het tumors, eight Pax5-het/Aid-KO tumors, and paired samples of germline tail DNA as a reference." (PMID 31804490, 2019). "In the present study we demonstrated that both these aberrancies are not only necessary to drive leukemia, but they are a direct consequence of the expression of the PAX5 fusion protein, which can a) repress the activity of endogenous PAX5 and b) activate STAT5 through LCK." (PMID 25595912, 2015). "To examine whether a similar increase in PD-1 expression with leukemia evolution is observed in other mouse leukemia models, we evaluated, together with B-ALLs appearing in Pax5+/− (n = 14) animals, those that originated in transgenic Sca1-ETV6-RUNX1 (n = 3) mice." (PMID 41283237, 2025). "Nevertheless, when crossed to additional leukemia predisposing backgrounds (e.g. Ebf1 or Ikzf1, Stat5b or BCR-ABLp190) or challenged through external stressors (e.g. infection exposure or antibiotics) Pax5± mice develop an aggressive BCP-ALL that closely resembles the human disease." (PMID 40394211, 2025). "Thus, modifying the gut microbiome through bacterial depletion impacts B-ALL development in Pax5+/– mice but not in these other leukemia-predisposed strains." (PMID 37620322, 2023).
leukemia (continued). "However, we did find a heterozygous point mutation in Pax5 (P80R) in three out of the four analyzed secondary WT leukemias but not in the Vav3−/− leukemias." (PMID 35650206, 2022). "Moreover, the Pax5::Jak2 mouse model generates a more aggressive leukemia through loss of the Pax5 WT allele caused by uniparental disomy of the Pax5::Jak2 allele, but the PAX5 WT allele is normally retained in human PAX5::JAK2 leukemia." (PMID 36387144, 2022). "Taking all this together, a clear leukemia-initiating effect of constitutively active IL-7Rα could be observed in different mouse models as well as in human hematopoietic progenitors, with similarities to Ph-like and/or PAX5 P80R BCP-ALL subtypes." (PMID 35294722, 2022). "Mice with heterozygous loss of Pax5 show normal B cell development and never develop leukemia." (PMID 36387144, 2022). "Hence, the mouse Pax5Jak2/+ model appears to generate, through loss of the wild‐type Pax5 allele, a more aggressive leukemia and thus does not recapitulate all aspects of the human PAX5‐JAK2+ B‐ALL disease." (PMID 35156727, 2022). "Interestingly, recent works from Sanchez-Garcia and colleagues demonstrated that leukemia initiation and progression can be triggered upon natural infection exposure or by altering the gut microbiome in Pax5 heterozygous mice as well as in the Sca1-ETV6-RUNX1 model." (PMID 34771671, 2021). "However, a complete block of differentiation as imposed by RAG deficiency, do not result in leukemia formation in collaboration with activated STAT5 as efficiently as heterozygote loss of Pax5 in mouse models." (PMID 31381561, 2019). "While germline loss-of-function mutations are a cause of familial pre-B ALL, demonstrating that PAX5 deficiency can ultimately initiate leukemogenesis, loss of PAX5 activity is not by itself sufficient, and development of leukemia requires additional cooperating mutations." (PMID 30216339, 2018). "Furthermore, PAX5 has been recently reported to be target of aberrancies, including mutations, deletions and translocations, in about 30% of pediatric patients affected by BCP-ALL, the most frequent leukemia subset in children." (PMID 25595912, 2015). "Indeed, modulation of PAX5 levels in lymphoid progenitors can direct differentiation into fully mature B cells, or in case of low PAX5 expression, to an intermediate biphenotypic state, very similar to the one found in biphenotypic leukaemia." (PMID 23828660, 2013). "Genes that have been reported as abnormally methylated in leukemia, including CPEB1, BLK, FLT3, PAX5, EBF1, HDACs, IKZF1, RB, etc., were also detected in this study." (PMID 41226303, 2025). "In the case of this patient, immunohistochemistry was performed, which showed positivity for TdT (lymphoid precursor cell marker) and PAX5 (nuclear marker for B cell), corroborating the diagnosis of B-LBL/leukemia." (PMID 38223368, 2024). "Two Early-Pro cases, Ph28-D and Ph50-D, harbored concurrent deletions of EBF1, PAX5, RUNX1 and CDKN2A/B and clustered between Early-Pro and Late-Pro leukemias in PCA." (PMID 37337105, 2023). "The test on human patients reveals mutations in KRAS, PTPN11, PAX5, NRAS, and JAK3 in divergent types of B-ALL involving PAX5-ELN B-ALL and leukemia due to PAX5-rearrangement." (PMID 37335685, 2023). "C3 leukemias also showed marked upregulation of B-cell transcription factors, EBF1 and PAX5, and B-cell receptor signaling genes." (PMID 37337105, 2023). "However, the more aggressive mouse Pax5Jak2/+ tumor model allowed us to identify the Pax5‐Jak2 protein as an important oncogenic driver of leukemia development, which might have been more difficult to demonstrate in the presence of the competing full‐length Pax5 protein." (PMID 35156727, 2022). "This study also identified immune disease-related genes associated with somatic mutations such as MYD88 and BCL10 in NF-κB signaling, CD79B, PAX5, and BCR in B-cell development, and MYH11, RUNX1, and TET2 in leukemia." (PMID 29937999, 2018).
leukemia (continued). "As immune disease-related genes, MYD88 (81.4%) and BCL10 (25.9%) in NF-ĸB signaling, CD79B (59.2%), PAX5 (22.2%), and BCR (7.4%) in B-cell development, and MYH11 (25.9%), RUNX1 (7.4%), and TET2 (7.4%) in leukemia were observed." (PMID 29937999, 2018). "Decreased expression of Pax5 and Ebf1 also occurred in the post-CD19 CAR leukaemia from patient ALL_H0140 demonstrating lineage." (PMID 27460500, 2016). "The authors postulate that deletions of the following genes ETV6, VPREB1, CDKN2A/B, TBL1XR1, PAX5 as well as BTLA and CD200 are very early and essential events in leukemia development." (PMID 27933341, 2016). "Similarly, we showed that PAX5, EBF1, CD72 and TCL1A are tightly correlated in the capacity to distinguish lymphoblastic and myeloblastic characteristics also in the presence of MLL mutations illustrating the importance of B-cell receptor signaling pathway in this subset of leukemias." (PMID 19549311, 2009). "This tumor was composed of immature lymphoma/leukemia (Pax5+, TdT+, CD3-, Mac2-) and myelomonocytic leukemia (Pax5-, TdT-, CD3-, Mac2+)." (PMID 16563162, 2006). "Along these lines, transplantation of 1 × 105Pax5± pre-BII cells (n = 5 receiving Pax5± and n = 5 receiving WT cells) did not give rise to leukemia development in an aging mouse cohort, which was monitored up to a mouse age of 82 weeks." (PMID 40394211, 2025). "This increase in PD-1 expression is also apparent across diverse molecular B-ALL subtypes in human B-ALL samples, although in mouse and human leukemias PD-1 expression is not solely dependent on PAX5 activity." (PMID 41283237, 2025). "Accordingly, the studies on Pax5/- and Sca1-ETV6-Runx1 mice have permitted the demonstration, for the first time, of the key role of genetic factors in contributing to affecting GM and how such variations can impact HS and leukemia development." (PMID 38612738, 2024). "We have previously shown that altering the gut microbiome with antibiotic treatment elicits leukemia in Pax5+/− mice, even in the absence of an infectious trigger (i.e., in specific pathogen-free conditions, SPF)." (PMID 37620322, 2023). "This suggests a BCR-ABL1+ precursor clone, which lacked PAX5 inactivation and RUNX1 mutation, independently gave rise to both Late-Pro leukemia at diagnosis and Early-Pro leukemia at relapse." (PMID 37337105, 2023). "Infections have always been a usual suspect taken into account to explain the development of childhood leukemia, but this possibility had not been proven experimentally until Pax5 heterozygous mice were exposed to common infections." (PMID 35886910, 2022). "Carriers of germline PAX5 mutations are susceptible to acquiring ALL, but the presence of the mutation does not seem to be sufficient for development of overt leukemia." (PMID 35294722, 2022). "Pax5 heterozygous mice do not develop leukemia when housed in specific pathogen free (SPF) conditions however they are prone to precursor B ALL when exposed to common pathogens and sequencing of these leukemias identified recurrent Jak3 mutations." (PMID 34484175, 2021). "In this cluster, the over-expression of PAX5 and TCL1A could also indicate presence of malignant immune cells as these genes are often found in leukemia and likely to contribute to oncogenesis BCL6." (PMID 32070336, 2020). "In order to explore if PAX5 is part of other regulatory networks not directly targeted in leukemia, we performed ChIP-seq experiments to identify FLI1 binding sites in 230–238 mouse Pre-B cells." (PMID 31381561, 2019). "Ebf1 and Pax5 deletions, though not sufficient to induce leukemia of their own accord, can each induce leukemia in mice with constitutive STAT5b activation." (PMID 23487523, 2012). "This increase in PD-1 expression is also apparent across diverse molecular B-ALL subtypes in human B-ALL samples, although in mouse and human leukemias PD-1 expression is not solely dependent on PAX5 activity, and further studies should help to identify the mechanisms involved." (PMID 41283237, 2025).